MBP (myelin basic protein)
Description:
The classic group of MBP isoforms (isoform 4-isoform 14) are with PLP the most abundant protein components of the myelin membrane in the CNS. They have a role in both its formation and stabilization. The smaller isoforms might have an important role in remyelination of denuded axons in multiple sclerosis. The non-classic group of MBP isoforms (isoform 1-isoform 3/Golli-MBPs) may preferentially have a role in the early developing brain long before myelination, maybe as components of transcriptional complexes, and may also be involved in signaling pathways in T-cells and neural cells. Differential splicing events combined with optional post-translational modifications give a wide spectrum of isomers, with each of them potentially having a specialized function. Induces T-cell proliferation.
Tractability: Antibody: UniProt places it where antibodies can reach, with medium confidence; its Gene Ontology location is reachable by antibodies, with medium confidence; the Human Protein Atlas places it where antibodies can reach. PROTAC: its protein half-life has been measured.
Gene: Protein-coding gene on chromosome 18 (76,978,827 to 77,133,683, reverse strand). Ensembl gene ENSG00000197971.
Subcellular location: Myelin membrane; Nucleus (Isoform 3)
Subcellular location (Human Protein Atlas): Plasma membrane
Pathways (Reactome):
Developmental Biology: EGR2 and SOX10-mediated initiation of Schwann cell myelination
Gene Ontology:
Molecular function: calmodulin binding; lipid binding; protein binding; structural constituent of myelin sheath
Biological process: myelin assembly; axon ensheathment; central nervous system development; chemical synaptic transmission; immune response; membrane organization; myelination
Cellular component: myelin sheath; protein-containing complex; cell surface; compact myelin; cytosol; internode region of axon; neuronal cell body; nucleus; synapse
Genetic constraint (gnomAD): Loss-of-function variants: 15 observed, 34.12 expected, observed/expected ratio (o/e) 0.44, 90% interval 0.29 to 0.68. The upper end of that interval is the gene's LOEUF score, 0.68, which puts it in group 2 of 6, group 1 being the genes least tolerant of losing a copy. Missense variants: 374 observed, 406.39 expected, observed/expected ratio (o/e) 0.92, 90% interval 0.85 to 1. Synonymous variants: 142 observed, 161.85 expected, observed/expected ratio (o/e) 0.88, 90% interval 0.76 to 1.01.
Homologues: Orthologues: chimpanzee MBP (99% identical), macaque MBP (87% identical), pig MBP (86% identical), rabbit MBP (79% identical), rat Mbp (72% identical), mouse Mbp (72% identical), dog MBP (71% identical), tropical clawed frog mbp (63% identical), guinea pig MBP (52% identical), zebrafish mbpa (16% identical).
Diseases named in the same sentence as MBP in open-access papers:
MBP is named in the same sentence as 288 diseases in open-access papers, as found by Europe PMC text mining. Sharing a sentence is not in itself a finding about the gene and the disease. The quoted sentences say what the papers report.
multiple sclerosis (224 papers, 2005 to 2025). A progressive autoimmune disorder affecting the central nervous system resulting in demyelination. "Increased abundance of myelin basic protein (MBP) is linked to multiple sclerosis and other CNS disorders, causing autoimmune demyelination, neuronal toxicity, and impaired myelin formation and maintenance." (PMID 41441337, 2025). "MBP is associated with the autoimmune disease multiple sclerosis, being one of the key autoantigens implicated in the disease." (PMID 40391216, 2025). "This protective effect of DMF on white matter has been also observed in mouse models of multiple sclerosis, where the compound showed potential to suppress demyelination and axonal loss by quantifying MBP." (PMID 39334781, 2024). "MBP encodes for myelin basic protein, which is the major target of T cells in lesions of multiple sclerosis (MS) patients and the animal model of experimental autoimmune encephalomyelitis." (PMID 36609529, 2023). "It is believed that the development of multiple sclerosis is associated with the hydrolysis of proteins, including MBP of the myelin sheath of nerve tissues." (PMID 36009424, 2022). "It is scientifically proved that CTSG causes the degradation of an immuno-2dominant myelin basic protein (MBP) epitope (MBP85-99) which causes its immuno-pathogenesis in multiple sclerosis." (PMID 35002435, 2022). "Variants in the TK2 gene, associated with mitochondrial DNA depletion syndrome 2 (OMIM#609560), and in the MBP gene, associated with susceptibility to multiple sclerosis (OMIM#126200), were also found." (PMID 33815474, 2021). "The MBP gene encodes a transmembrane IgE receptor associated with susceptibility to multiple sclerosis (OMIM#126200) and the TYK2 gene encodes a tyrosine kinase associated to type I and III interferon signaling, playing a role in antiviral immunity." (PMID 33815474, 2021). "MBP is implicated in auto-immune responses within the human CNS, and is thought to be a target for T cell activity in multiple sclerosis and other demyelinating or degenerative disorders." (PMID 30577490, 2018). "Using IEDB, YAC is partially mapped to ASQKRPSQRHGSKYLATAST, an HLA-DR-restricted MBP epitope implicated in multiple sclerosis in humans." (PMID 26270649, 2015). "Alterations in MBP have been linked to both neurologic disorders in which stress seems to play a role, such as multiple sclerosis and psychiatric disorders (such as bipolar disorder)." (PMID 26251769, 2015). "Genetic linkage and association analyses suggested that a genetic predisposition to multiple sclerosis was closely linked to the MBP gene in this population." (PMID 24324888, 2013). "For example we found, together with David Wraith and colleagues, that AEP makes a cleavage in the middle of a well characterised ‘self’ epitope in myelin basic protein (MBP) that has been linked to the pathogenic T cell response in multiple sclerosis." (PMID 21782984, 2012). "Multiple sclerosis (MS) is associated with pathogenic autoimmunity primarily focused on major CNS-myelin target antigens including myelin basic protein (MBP), proteolipidprotein (PLP), myelin oligodendrocyte protein (MOG)." (PMID 22316121, 2012). "MBP is one of the main autoantigens of the myelin sheath, being implicated in multiple sclerosis (MS) and animal models of autoimmune neurological disorders." (PMID 21647440, 2011). "MLE-mediated ligand exchange depends largely only on the availability and we have shown that abundant pathogenic autoantigens, such as multiple sclerosis-associated myelin basic protein (MBP), can be transferred by this mechanism onto MHC II." (PMID 19738910, 2009). "MBP, found in both network 3 and 4, is associated with genetic susceptibility to multiple sclerosis [OMIM:126200]." (PMID 19799774, 2009).
multiple sclerosis (continued). "Western blotting analysis revealed significantly elevated protein expression of the pro-inflammatory cytokine TNF-α (a critical factor in multiple sclerosis with myelinolytic effects) and reduced expression of myelin-associated proteins MBP and MAG in Cuprizone-fed mice compared to controls." (PMID 40563355, 2025). "MBP is associated with the formation of myelin in the central nervous system and has long been implicated as a factor in the pathogenesis of the autoimmune neurodegenerative disease multiple sclerosis (MS)." (PMID 39064631, 2024). "Furthermore, results from an experimental rodent model for multiple sclerosis also suggest the degeneration of myelin in different strains, by evaluating the MBP loss in different variants of mice over time." (PMID 37892207, 2023). "In one fulminant case of multiple sclerosis, known as ‘Marburg variant,’ deimination of 18 of 19 arginyl residues to citrulline within acutely demyelinating plaque led to a dramatic decrease in MBP positive charge." (PMID 36896314, 2022). "However, the safety of this method is still under debate, as autoimmune diseases, such as multiple sclerosis, are caused by hyperreaction to intrinsic antigens, such as MBP." (PMID 34580655, 2021). "One cannot exclude, that similar to mouse models of EAE or SLE, some people genetically predisposed to MS can develop outset of multiple sclerosis only after their autoimmunization by MBP and products of its hydrolysis, while predisposed to SLE pathology only after immunization with DNA." (PMID 28780774, 2017). "Despite its potential role in MS, none of the large genome‐wide association studies (GWAS)(International Multiple Sclerosis Genetics C, 2013; International Multiple Sclerosis Genetics C, Wellcome Trust Case Control C, 2011) have found any variants in MBP that predict MS risk." (PMID 28413712, 2017). "Our findings suggest that spontaneous expression of interferon-β-inducible genes in peripheral blood mononuclear cells from untreated multiple sclerosis patients and treatment with interferon-β are associated with reduced myelin basic protein-induced T-cell responses." (PMID 25738751, 2015). "Hspbp1 may facilitate antigen processing by regulating the chaperone function of Hsp70, which has been associated with the presentation of myelin basic protein though MHC class II in multiple sclerosis." (PMID 16670020, 2006). "EBNA-1 was also shown to harbor epitopes that share similarities with myelin basic protein, the implicated autoantigen in multiple sclerosis, and with La antigen, which may trigger Sjögren’s syndrome, in addition to Sm (the small nuclear ribonucleoprotein) which may play a role in SLE." (PMID 38638687, 2024). "Given that MBP autoantibodies are implicated in demyelinating disorders such as multiple sclerosis and often arise following more severe CNS insults, this absence suggests that repetitive low-level blast exposures may not produce the same extent of myelin injury as higher-intensity blasts." (PMID 39769446, 2024). "Moreover, ACPA cross-reactivity to citrullinated peptides from myelin basic protein (MBP) was analyzed, as citrullinated MBP recently was described to be associated with multiple sclerosis, and some degree of sequence homology between MBP and citrullinated EBNA exists." (PMID 35323194, 2022). "In the past, such a TCRL antibody was selected towards HLA-DR2 molecules complexed with an immunodominant myelin basic protein (MBP) peptide (residues 85–99) and was used for visualization of MBP T-cell epitopes in multiple sclerosis lesions." (PMID 39496501, 2025). "Myelin basic protein (MBP) concentrations in CSF provide a reliable biomarker of demyelination and correlate with disease severity in multiple sclerosis." (PMID 41009644, 2025). "Both myelin basic protein (MBP) and autoantibodies against MBP have been targeted for aptamer development as potential multiple sclerosis (MS) therapy." (PMID 38474636, 2024).
multiple sclerosis (continued). "MBP autoantibody-associated encephalitis has recently been described in a human patient with suspected multiple sclerosis (MS), CSF pleocytosis, and high levels of MBP antibodies." (PMID 39403212, 2024). "MBP has long been investigated as a factor in the pathogenesis of the autoimmune neurodegenerative disease multiple sclerosis, and it is clear that MBP and its functions in myelin formation and long-term maintenance are associated with MS." (PMID 38540780, 2024). "Antibodies associated with multiple sclerosis (MS) and systemic lupus erythematosus (SLE) enzymatically degrade myelin basic protein (MBP)." (PMID 38790969, 2024). "Our study underscores the role of anti-MBP in secondary morbidity among TSCI patients, highlights its association with multiple sclerosis and Idiopathic polyneuropathy, both characterized by a pathological demyelination." (PMID 39261594, 2024). "Model antigens functioned as SARS-CoV-2 spike glycoprotein (UniProt: P0DTC2) and SARS-CoV-2 nucleocapsid protein (UniProt: P0DTC9) related to a COVID-19 infection, MBP (UniProt: P02686) for multiple sclerosis, and AChRα (UniProt: P02708) for myasthenia gravis." (PMID 38779658, 2024). "In patients with multiple sclerosis, the Gal-9/Tim-3 interaction favors apoptosis of myelin basic protein-specific T lymphocytes, which correlates with reduced disease progression." (PMID 38957462, 2024). "The blood plasma of systemic lupus erythematosus (SLE) and multiple sclerosis (MS) patients usually contains abzymes that hydrolyze oligosaccharides, myelin basic protein (MBP), DNAs, RNAs, and histones (and references therein)." (PMID 39337388, 2024). "MBP is a well-known marker to detect demyelination in multiple sclerosis, human auditory nerve, and some other neurodegenerative diseases." (PMID 37239226, 2023). "NOD2 variants are associated with a high level of IL-17 in PBMC from patients with multiple sclerosis or with ocular toxoplasmosis stimulated with myelin-basic protein and soluble Toxoplasma antigen, respectively." (PMID 36795715, 2023). "The majority of patients with rheumatoid arthritis produce anti-citrullinated protein antibodies, and we have recently shown that citrullination of myelin basic protein influences its antigenicity in the context of multiple sclerosis." (PMID 38173716, 2023). "Myelin basic protein (MBP) is one of the key structural elements of the myelin sheath and has autoantigenic properties in multiple sclerosis (MS)." (PMID 36980286, 2023). "The proportion of MBP-reactive T cells increases after injury, which reach infiltration levels that approximate those identified in patients with multiple sclerosis." (PMID 38293650, 2023). "Citrullination is known to render self-proteins immunogenic in rheumatoid arthritis, and we have recently shown that citrullination of myelin basic protein influences its antigenicity in the context of multiple sclerosis." (PMID 38173716, 2023). "Antibodies with proteolytic activity against myelin basic protein have been identified and characterized in detail in a number of autoimmune diseases, including multiple sclerosis, systemic lupus erythematosus, as well as in autism and schizophrenia." (PMID 37431466, 2023). "For example, antibodies specific to myelin basic protein (MBP) derived from the blood plasma of systemic lupus erythematosus and multiple sclerosis patients can hydrolyze four oligopeptides (17-, 19-, 21-, and 25-mer OP) corresponding to MBP epitopes." (PMID 37762643, 2023). "This was further evidenced by the presence of antibodies specific to myelin basic protein (MBP) in their sera and MBP-specific T cells in their spleens, similar to what is often seen in models of multiple sclerosis." (PMID 38005878, 2023).
multiple sclerosis (continued). "Antibodies with proteolytic activity against MBP have been identified and characterized in detail in a number of autoimmune diseases, including multiple sclerosis, systemic lupus erythematosus, as well as in autism, schizophrenia and bipolar disorder." (PMID 37431466, 2023). "Myelin basic protein (MBP) is an important structural unit of the myelin sheath of axons and is associated with many neurodegenerative diseases, in particular, multiple sclerosis (MS)." (PMID 36980286, 2023). "Electrophoretically homogeneous IgGs against H1, H2A, H2B, H3, H4, MBP, and DNA were derived from sera of multiple sclerosis (MS) patients by several affinity chromatographies." (PMID 36009424, 2022). "IgGs against five histones, MBP, and DNA were obtained from the sera of multiple sclerosis (MS) patients using several affinity chromatographies." (PMID 36289924, 2022). "Antibodies to MBP appear in violation of the integrity of myelin during stroke, brain injury, multiple sclerosis, systemic lupus erythematosus, autism, and schizophrenia." (PMID 35806400, 2022). "Polyclonal IgGs from the blood of HIV-infected patients and patients with multiple sclerosis effectively split the five human histones and MBP." (PMID 36289924, 2022). "Antigenic peptides of both MAP and Epstein-Barr virus (EBV) are recognized by anti-myelin basic protein in multiple sclerosis individuals supporting the concept that both MAP and EBV trigger multiple sclerosis autoimmunity through a common target." (PMID 35655048, 2022). "For example, anti-Myelin Basic Protein (MBP) have been reported in multiple sclerosis and systemic lupus erythematosis (SLE)." (PMID 36264970, 2022). "Using IgGs of HIV-infected and multiple sclerosis patients against five individual histones (H1–H4), MBP, and DNA, it was first shown that abzymes against each of these antigens effectively recognize and hydrolyze all three antigens: histones, MBP, and DNA." (PMID 35897678, 2022). "This preclinical study supports our finding of anti-MBP autoantibody in a subgroup of women with fibromyalgia and women with painful multiple sclerosis." (PMID 35496906, 2022). "It is likely that in this case, MBP-hydrolyzing IgG can damage the myelin sheath of axons, similarly to in multiple sclerosis, thus violating the integrity of neuronal circuits." (PMID 35806400, 2022). "MBP marks oligodendrocytes and encodes the protein of the myelin membrane in the CNS and several studies have shown that MBP is a biomarker for multiple sclerosis." (PMID 36569494, 2022). "MBP has long been studied as a factor in the pathogenesis of the autoimmune neurodegenerative disease multiple sclerosis (MS)." (PMID 34889995, 2022). "The involvement of Myelin Basic Protein (MBP) in Multiple Sclerosis (MS) has been widely discussed in the literature." (PMID 35795217, 2022). "In lymphoblastoid B cells, AEPs participate in the degradation of myelin basic protein (MBP) and thus its conversion into antigenic peptides that are associated with multiple sclerosis." (PMID 36142134, 2022). "Herein, we present a study on the role of the sequence and structure of synthetic MBP peptides that have been used to identify specific antibodies in Multiple Sclerosis patient sera." (PMID 35795217, 2022). "This R2*QSM technique is validated against quantitative histology—optical density of myelin basic protein and Perls’ iron histological stains of rim and core of 10 ex vivo multiple sclerosis lesions, as well as neighboring normal appearing white matter." (PMID 35736875, 2022). "Anti-histone and chimeric anti-histone-DNA antibodies can hydrolyze MBP in sheath neural tissues, promoting the development of multiple sclerosis." (PMID 36009424, 2022). "Considering this, the analysis of possible enzymatic cross-reactivity of abs-abzymes against MBP, histones, and DNA is critical for analyzing the beginning and progress of multiple sclerosis." (PMID 36009424, 2022).